CXCR4 (C-X-C motif chemokine receptor 4)
Diseases named in the same sentence as CXCR4 in open-access papers (continued):
Sharing a sentence is not in itself a finding about the gene and the disease.
neuroblastoma (continued). "Moreover, significant reduction in tumor size and complete remission have been observed with CCR2b-GD2-CAR T cells and CXCR4-EGFRvIII-CAR NK cells infused in mice bearing CCL2 producing GD2 neuroblastoma or CXCL12 secreting EGFRvIII glioblastoma cells, respectively." (PMID 30420855, 2018). "Thus, studying the role of CXCR4 in the metastasis of neuroblastoma is of great importance." (PMID 24932293, 2014). "In our study, Foxp3 and CXCR4 were expressed in neuroblastoma cells; therefore, it may be possible that Foxp3 expressed in these cells upregulated CXCR4 and contributed to the higher frequency of neuroblastoma." (PMID 24932293, 2014). "In addition, the results suggest that CXCR4 and Foxp3 may present as potential targets for neuroblastoma chemotherapy." (PMID 24932293, 2014). "The positive correlation of PGK1 and CXCR4 expression in neuroblastoma patients as well as the downregulation of PGK1 through inhibition of the CXCR4 receptor, which we found in our in vitro studies, are indicators for a causal interaction between the PGK1 pathway and the CXCR4/SDF1 axis." (PMID 24376734, 2013). "Most importantly, R+D ‘pre-treatment’ compared to control (vehicle) treatment proficiently reduced the elevated CXCR4, BMI1 and NANOG protein expression in spheroid cultures in both neuroblastoma cell lines." (PMID 36980635, 2023). "Co-expression of CXCR4, specifically the 47kD isoform, and CXCR7 significantly and selectively increased neuroblastoma dissemination toward the bone marrow." (PMID 34831167, 2021). "Established and experimental adverse prognostic factors of neuroblastoma include amplification of NMYC, expression of the chemokine receptor CXCR4 that is responsible for metastatic homing and the hypoxia-dependent water channel aquaporin 1 (AQP1)." (PMID 33671521, 2021). "CXCR4 favors neuroblastoma diffusion to liver and lungs, whereas CXCR7 promotes liver and adrenal gland dissemination, both CXCR4 and CXCR7 increase BM invasion." (PMID 33937018, 2021). "In turn, the secretome of bone marrow MSCs was shown to promote the expression of the 47 kDa CXCR4 isoform and also increased MMP-9 secretion, expression of integrin α3 and integrin β1, supporting the invasive potential of neuroblastoma cells." (PMID 34831167, 2021). "In neuroblastoma cell lines, overexpression of CXCR7 was shown to limit cell growth and CXCR4/CXCL12-mediated chemotaxis." (PMID 30420855, 2018). "Exposure for 24 h to 10 nM BK sensitized neuroblastoma cells to low doses of SDF-1 (3 ng/mL), suggesting that BK increases the sensitivity of CXCR4 responsiveness to SDF-1 facilitating its activation." (PMID 29867502, 2018). "This suggests a major role of the 47 kDa CXCR4 isoform in responding to the MSC secretome stimuli, in bone marrow metastasis of neuroblastoma." (PMID 25774696, 2015). "A panel of 20 neuroblastoma cell lines was examined for their invasion potential towards MSC-conditioned RPMI and their CXCR4 expression profiles." (PMID 25774696, 2015). "There was another clear upregulation of CXCR4 expression in SH-SY5Y cells following co-culture with macrophages, an alternative source of TNF-α in the neuroblastoma microenvironment." (PMID 25503960, 2015). "In the present study, CXCR4 was found to be highly expressed in the LAN-5 and SK-N-SH neuroblastoma cell lines." (PMID 24932293, 2014). "The present study aimed to examine the expression of CXCR4 and Foxp3 in the LAN-5 and SK-N-SH neuroblastoma cell lines." (PMID 24932293, 2014). "Notably, the expression of CXCR4 was decreased after the cells were treated with chemotherapy drugs, CTX and THP, in association with the inhibition of cell proliferation; therefore, the expression of CXCR4 may be involved in the metastasis of neuroblastoma." (PMID 24932293, 2014). "Samples from 22 patients with neuroblastoma that were surgically treated at the University Medical Center Hamburg-Eppendorf were evaluated for expression of PGK1 and CXCR4 using immunohistochemistry." (PMID 24376734, 2013).
neuroblastoma (continued). "The aim of the current study was to evaluate the role of PGK1 expression in neuroblastoma patients, to determine the impact of PGK1 expression levels on survival, and to correlate PGK1 expression with CXCR4 expression and bone marrow dissemination." (PMID 24376734, 2013). "Immunocytochemistry, proliferation and expression analysis of CXCR4 and PGK1 were performed in neuroblastoma cell lines." (PMID 24376734, 2013). "Based on this, the possibility that in neuroblastoma cells an E3 ligase other than AIP4, possibly Cul-5, mediates modification of CXCR4 is intriguing." (PMID 20028517, 2009). "Moreover, hypoxia can significantly increase known adverse factors in neuroblastoma such as NMYC, CXCR4, PGK1 and AQP1, amongst others, leading to tumor progression and increased metastases." (PMID 35328549, 2022). "In our previous study, both CXCR4 and CXCR7 were found to express in neuroblastoma cell lines." (PMID 33838662, 2021). "CXCR7 was involved in increasing neuroblastoma migration via alternative receptor of SDF-1 in the absence of CXCR4, but has no role in regulating normal cell migration and adhesion." (PMID 33838662, 2021). "The C-X-C chemokine receptor type 4 (CXCR4) and its ligand, α-chemokine stromal-derived factor-1 (SDF-1), secreted by BM stroma supposedly participate in establishment of BM metastasis by neuroblastoma cells." (PMID 29867502, 2018). "Furthermore, there were significant correlations between the high level of NF-κB-p65, CXCR4 expression, clinical metastasis and INSS stages, which indicated the utility of NF-κB and CXCR4 as predictive biomarkers and therapeutic targets in neuroblastoma." (PMID 25503960, 2015). "Here, we demonstrate internalization of extracellular gp120 in a manner partially independent of binding to its coreceptor CXCR4 by F11 neuroblastoma cells and cultured dorsal root ganglion neurons." (PMID 25636314, 2015). "A further study found that the CXCR4/SDF1 axis strongly enhances cell growth without increasing in vivo invasion in neuroblastoma progression." (PMID 24376734, 2013). "Kelly and SH-EP Tet-21/N neuroblastoma cell lines were examined for expression of PGK1 and CXCR4." (PMID 24376734, 2013). "Others have suggested however that CXCR4 is not involved in chemotaxis of neuroblastoma cells and that SDF-1/CXCR4 signaling causes cell death." (PMID 20028517, 2009). "CXCR4 has been shown to display significant structural heterogeneity, yet to date no extensive analysis of CXCR4 secondary structure in neuroblastoma has been performed." (PMID 20028517, 2009). "It is compelling to speculate whether these two classes of isoforms respectively regulate opposing CXCR4 mediated responses such as, the proliferative and cytotoxic signaling in response to SDF-1 stimulation observed in two different neuroblastoma cell lines." (PMID 20028517, 2009). "In this study, we investigate to what extent the expression of AQP1 in neuroblastoma correlates with or is dependent on changing cellular factors such as differentiation, expression of know adverse factors such as NMYC and NCAM, and metastatic spread related to CXCR4." (PMID 33467498, 2021). "In this study, we investigate to what extent the expression of AQP1 in neuroblastoma correlates with changing cellular factors such as the hypoxic status, differentiation, expression of known adverse factors such as NMYC and NCAM, and CXCR4-related metastatic spread." (PMID 33467498, 2021). "AQP1 and not CXCR4 is the initiator of migration in neuroblastoma." (PMID 33467498, 2021). "A previous study indicated that a CXCR4/SDF-1α axis may be involved in attracting neuroblastoma cells to bone marrow, which was one of the favorable sites of metastasis formation by neuroblastoma; however, the mechanism responsible for its upregulation has not been completely elucidated." (PMID 25503960, 2015).
neuroblastoma (continued). "Although the interaction of the CXCR4/SDF1-PGK1 axis to our knowledge has not been researched for neuroblastoma, PGK1 might be a possible therapeutic target also for this tumor entity." (PMID 24376734, 2013). "For example, an in vitro study of neuroblastoma cell lines as well as patient samples, CXCR4 could not demonstrate a functional role, although it was expressed on bone marrow metastases." (PMID 24376734, 2013). "Besides acting as a cofactor for HIV, CXCR4 mediates the CXCL12-directed migration of cancer cells to metastatic sites through the promotion of angiogenesis and migration of tumor cells in breast, lung, ovarian, renal, prostate and neuroblastoma." (PMID 20376365, 2010). "Such a mechanism might involve proteasomal mediated modification of CXCR4, possibly with ubiquitin, which targets CXCR4 to the surface of neuroblastoma cells as opposed to lysosomal degradation." (PMID 20028517, 2009). "However, in an orthotopic model of neuroblastoma, which includes all steps of the metastatic process, CXCR4 is not sufficient to induce or increase metastasis, but fully manifest its growth promoting effects." (PMID 17925864, 2007). "The association of CXCR4 expression to site-specific metastasis, into BM of neuroblastoma-bearing patients, and the supportive effect of endothelial niche in Notch-dependent T-ALL cells maintenance, favor our hypothesis that Notch3/CXCR4 crosstalk directs “pre-leukemic” DP-cells to the BM." (PMID 30038265, 2018). "These cell lines showed good correlation between the expression of the 47 kDa CXCR4 isoform and clinical aggressiveness, as well as in vitro invasiveness, suggesting that the 47 kDa CXCR4, up-regulated by MSC secretome may mediate metastasis of neuroblastoma into the bone marrow in vivo." (PMID 25774696, 2015). "SH-SY5Y is a human neuroblastoma cell line expressing N-methyl-D-aspartic acid (NMDA) receptors, CXCR4, CCR5, and but not CD4, and can binds to gp120 proteins." (PMID 28392757, 2017). "Therefore, the high expression of CXCR4 and Foxp3 in LAN-5 and SK-N-SH cells and their subsequent downregulation following administration of the chemotherapy agents suggests that the chemokine receptors, CXCR4 and Foxp3, may be involved in the metastasis and tumor evasion of neuroblastoma." (PMID 24932293, 2014). "Additionally, despite reporting little to no basal surface expression of CXCR4 on the majority of neuroblastoma cells they examined one group has reported SDF-1 mediated chemotaxis and down-regulation of CXCR4 upon derivatizing one of their cell lines to overexpress CXCR4." (PMID 20028517, 2009).
metastatic disease (56 papers, 2010 to 2025). "Overexpression of CXCR4 has been implicated in aggressive and metastatic tumor phenotypes with poor clinical prognosis." (PMID 35177982, 2021). "In reported meta-analyses, CXCR4 expression has been associated with metastatic disease and poor survival." (PMID 33753872, 2021). "Because of the wealth of evidence implicating CXCR4's role in metastatic disease for a variety of malignancies, CXCR4 inhibition has been investigated for its potential for clinical application in cancer therapy." (PMID 21234386, 2011). "CXCL12/CXCR4 signaling has been implicated in the development of metastatic disease in PC and anti-chemokine therapies limit the initial establishment of bone metastases in mice models through targeting tumor stromal interactions in bone tumor microenvironment." (PMID 38239314, 2023). "In addition, the expression rate of CXCR4 in lymph node-positive metastatic disease was very high and CXCR4 expression was associated with poor disease prognosis." (PMID 36140541, 2022). "Furthermore, previous studies on PDAC tissue specimen suggested that CXCR4 expression might represent a valuable biomarker as evidence for an association between CXCR4 expression and metastatic disease as well as patients’ survival was found." (PMID 26091099, 2015). "The role that CXCR4 plays in the EMT is crucial in the pathogenesis of metastatic disease in both GEP and BP-NENs." (PMID 38791878, 2024). "It appears that SSTRs and CXCR4 maintain an antagonistic relationship that favors the latter in high-grade, dedifferentiated, and metastatic tumors." (PMID 38791878, 2024). "CXCR4 is a chemokine receptor known to highly express in MDA‐MB‐231 metastatic tumors.[qv: 12c,d] We confirmed that it is highly expressed in 231BR cells by flow cytometry and in metastatic tumors in the brain by immunostaining." (PMID 32154067, 2020). "CXCR4 is deregulated in several cancer types and appears to be important in CRC metastasis as suggested by increased CXCR4 mRNA and protein in liver and increased protein in lymph nodes in metastatic tumors compared to primary tumors." (PMID 32110952, 2020). "The SDF-1/CXCR4 pair is emerging as an increasingly important intermediary for the interaction between tumor cells and their environment, promoting both the metastatic disease as well as recruitment of immunosuppressive elements to the tumor." (PMID 30149659, 2018). "CXCR4 is often overexpressed in metastatic tumors and promotes the migration of invasive cells to tissues where local CXCL12 secretion is increased, such as bone, liver, brain and lung." (PMID 28666461, 2017). "CD117 and CXCR4 staining, however, was increased in patient bone metastatic tumors over levels seen in the primary tumor." (PMID 28690641, 2017). "This metastatic staining indicates that CD117 and CXCR4 likely either drive the colonization of metastatic cells, the growth of metastatic tumors, or possibly escape from dormancy." (PMID 28690641, 2017). "For example, larger samples should be analyzed to detect Lgr5 and CXCR4 expression not only in primary CRCs, but also in metastatic tumors." (PMID 27835894, 2016). "Our present results are consistent with the previous results that the inhibition of the CXCL12-induced CXCR4-mediated signaling suppressed the growth of both primary and metastatic tumors." (PMID 26083776, 2015). "The expression of CXCR4 was substantially higher in metastatic tumors than in the corresponding primary tumors from the same animal." (PMID 26318034, 2015). "The mean weight of metastatic tumors (in g) was dramatically lower in the Lenti-CXCR4-siRNA group than in the SW480 group (1.45±2.07 vs 2.25±2.51, P=0.000) and NC group (1.45±2.07 vs 2.11±2.38, P=0.000)." (PMID 24647809, 2014).
metastatic disease (continued). "Clinically, a phase I/II clinical trial has determined the tolerability and safety profile of repeated administration of a CXCR4 peptide antagonist in a small cohort of patients (n = 25) with advanced metastatic disease." (PMID 26237063, 2013). "CXCR4 expression has been identified as a predictive factor of worse outcome in some metastatic tumors and in malignant gliomas." (PMID 23322021, 2013). "High expression levels of CXCR4 are correlated with poor outcomes and also predict metastatic disease." (PMID 21234386, 2011). "There is growing evidence that overexpression of CXCR4 plays a significant role in development of metastatic disease, especially in directing tumor cells towards the preferential sites of metastases in sarcoma, lung and bone." (PMID 21234386, 2011). "The data include in vitro invasion and migration assays as well as xenograft models of metastatic disease in which blockade of CXCR4 with drugs, peptides, or antibodies can inhibit development and growth of metastases." (PMID 20102637, 2010). "Binding of SDF-1 to CXCR4 induces migration of cancer cells into normal tissue, where the cells proliferate and form metastatic tumors." (PMID 20953377, 2010). "Furthermore, the levels of lncRNAs as well as EGR1 and CXCR4 were greater in patients with metastatic disease than in patients with localized disease." (PMID 40635521, 2025). "Based on our results, we can speculate that the nuclear translocation of CXCR4 may also be relevant in the metastatic disease in STSs, and may provide additional treatment options in this late stage of the disease." (PMID 38893721, 2024). "However, the expression levels of SDF1α and CXCR4 in metastatic PCa post-RT, and their role in metastatic tumor regrowth after RT, remained unclear." (PMID 36831366, 2023). "Chemokine (C-X-C motif) receptor 4 (CXCR4) expression increases during progression of PCa and is associated with metastatic disease and poor survival CXCR4 selectively binds to stromal cell-derived factor 1 (SDF-1)/ CXCL12, also overexpressed in PC metastatic tissue compared to normal tissues." (PMID 31718684, 2019). "The CXCR4/CXCR12 axis has been shown to be a critical step in progression of several tumor types, including MM, in which increased expression of CXCR4 is linked to advanced metastatic disease with poor prognosis." (PMID 30544512, 2018). "In conclusion, by performing a comprehensive literature search and meta-analysis we could demonstrate that CXCR4 expression levels were related to metastatic disease and overall survival in patients with PDAC." (PMID 26091099, 2015). "CXCL12/CXCR4 transactivation of epidermal growth factor family receptors in lipid raft membrane microdomains on cell surface is thought to mediate tumor growth and subsequent development of metastatic disease." (PMID 24472670, 2014). "Furthermore, our data demonstrated that CX3CR1 deficiency suppressed macrophage expression receptors CCR2, VEGFR2, and CXCR4 (cell surface markers of angiogenic macrophages) in hepatic metastatic tumors." (PMID 24245985, 2013). "CXCR4 expression was observed in 64% (28/44) of therapy-naïve and 47% (7/15) of metastatic tumors." (PMID 23249693, 2012). "Additionally, CXCR4 nuclear staining has been detected in cells of metastatic tumors." (PMID 38893721, 2024). "TGFβ-1, CXCR4, BMP1, VCAN, and WNT2 are more expressed in original tumors compared to metastatic tumors, according to the data." (PMID 41348904, 2025). "A particularly exciting example is a C-X-C chemokine receptor type 4 (CXCR4) antagonist peptide-docetaxel conjugate, which self-assembles into nanoparticles targeting CXCR4-overexpressing metastatic tumors." (PMID 41425250, 2025). "We looked at the TGFβ-1, CXCR4, BMP1, VCAN, and WNT2 expression profiles in a few BC datasets related to primary and metastatic tumors." (PMID 41348904, 2025). "CXCR4 expression is upregulated in NSCLC and reported in SCLC models/cohorts, with higher levels in advanced/metastatic disease." (PMID 41383468, 2025).